SNAP25-AS1 (SNAP25 antisense RNA 1)
Gene: Long non-coding RNA gene on chromosome 20 (10,006,381 to 10,368,848, reverse strand). Ensembl gene ENSG00000227906.
Gene Ontology:
Biological process: SRP-dependent cotranslational protein targeting to membrane, signal sequence recognition
Cellular component: signal recognition particle, endoplasmic reticulum targeting